LINC01133 (long independently transcribed non-coding RNA 1133)
Synonyms: lncRNA-PAGBC
Gene: Long non-coding RNA gene on chromosome 1 (159,941,373 to 160,025,027, forward strand). Ensembl gene ENSG00000224259.
Diseases named in the same sentence as LINC01133 in open-access papers:
LINC01133 is named in the same sentence as 42 diseases in open-access papers, as found by Europe PMC text mining. Sharing a sentence is not in itself a finding about the gene and the disease. The quoted sentences say what the papers report.
gastric cancer (18 papers, 2018 to 2025). A primary or metastatic malignant neoplasm involving the stomach. "For example, LINC01133 inhibits the proliferation, invasion, and metastasis of gastric cancer cells by directly targeting miR-106-3p and then by inactivating the IPC/Wnt/β-catenin pathway." (PMID 40643495, 2025). "In gastric cancer and colorectal cancer, LINC01133 acts as a tumor suppressor and is downregulated in tumor cells, inhibiting the EMT process." (PMID 38987572, 2024). "For instance, LINC01133 inhibits epithelial–mesenchymal transition in gastric cancer cells and cancer metastasis via functioning as a sponge of miR-106a, thereby increasing the levels of adenomatous polyposis coli (APC)." (PMID 38195623, 2024). "LINC01133 and the pseudogene FER1L4 are inhibitors of gastric cancer progression, with reduced expression associated with a more aggressive tumour phenotype." (PMID 38355543, 2024). "For instance, the altered expression of LINC01133 in gastric cancer regulates the Wnt/β-Catenin signaling pathway through the miR-106a-3p/APC axis." (PMID 39519092, 2024). "For example, LINC01133 was found in the cytoplasm of gastric cancer cells, interacting with miR-106a-3p to inactivate Wnt signaling and inhibit gastric cancer metastasis." (PMID 36672487, 2023). "Similar as we had found, linc01133 were significantly upregulated in gastric cancers compared to that in the normal gastric tissues, but having little impact on the outcome of the overall survival or the disease-free survival of gastric cancer patients." (PMID 35017464, 2022). "We subsequently confirmed the upregulation of linc01133 by 2.54-fold (median change) in gastric cancer tissues compared to normal gastric tissues (P = 0.048)." (PMID 35017464, 2022). "In this study, we found that linc01133 was upregulated combining our microarray data, clinical gastric cancer samples validation and TCGA data bioinformatic analysis." (PMID 35017464, 2022). "Through bioinformatics analysis and luciferase reporter gene analysis, this study identified miR-106a-3p as the direct target of LINC01133, indicating that LINC01133, as the ceRNA of miR-106a-3p, plays a role in the progression of gastric cancer." (PMID 35529267, 2022). "Collectively, these findings indicated that linc01133 promoted proliferation and cell cycle transition of gastric cancer cells." (PMID 35017464, 2022). "Studies have reported that LINC01133, which is mainly enriched in the cytoplasm of gastric cancer cells, binds to miR-106a-3p and promotes the expression of proteins of the anaphase promoting complex (APC)." (PMID 35747817, 2022). "A recent study found that the expression of lncRNA LINC01133 decreased in gastric cancer tissues and gastric cancer cell lines, and its low expression was positively correlated with the progression and metastasis of gastric cancer." (PMID 35529267, 2022). "For instance, LINC01133 functions as a ceRNA in gastric cancer by sponging miR-106a-3p to liberate APC." (PMID 33407499, 2021). "For example, Yang et al38 found that LINC01133 inhibited gastric cancer progression and metastasis by acting as a ceRNA for miR‐106a‐3p to regulate APC expression and the Wnt/β‐catenin pathway." (PMID 32583631, 2020). "For example, LINC01133 inhibits gastric cancer progression by sponging miR-106a-3p to regulate APC expression and the Wnt–β-catenin pathway." (PMID 33230459, 2020). "For further validation TCGA RNA-seq expression data for PCAT18, DANCR, and LINC01133 in stomach cancer and normal tissues were analyzed." (PMID 30518158, 2018). "The expression of PCAT18 and LINC01133 was down-regulated in stomach cancer tissues (p = 6.35 × 10−19 and p = 0.3.40 × 10−7, respectively; validation 3)." (PMID 30518158, 2018). "LINC01133 has been shown to be down-regulated in gastric cancer cell lines." (PMID 36042493, 2022). "Thus, LINC01133 up-regulation can suppress development of gastric cancer through decreasing expression of miR-576-5p and enhancing SST levels." (PMID 36042493, 2022).
gastric cancer (continued). "Furthermore, linc01133 expression was significantly increased in four out of the five gastric cancer cell lines examined compared to the immortalized normal gastric epithelial cell GES-1." (PMID 35017464, 2022). "In both in vitro and in vivo studies, linc01133 was shown to promote gastric cancer cell growth." (PMID 35017464, 2022). "Thus, our study unveiled the function and mechanism of linc01133 regulating cell cycle progression in gastric cancer." (PMID 35017464, 2022). "However, it is not well understood how linc01133 regulate the growth of gastric cancer cells." (PMID 35017464, 2022). "To study the function of linc01133, we overexpressed or knocked down linc01133 in AGS and HGC27 gastric cancer cell lines." (PMID 35017464, 2022). "We confirmed the up- and down-regulation of nucleus YAP1 by linc01133 overexpression or knockdown respectively in MKN45 and AGS gastric cancer cell lines." (PMID 35017464, 2022). "For example, LINC01133 tends to localize in both the nucleus and cytoplasm in ovarian cancer, and it tends to localize in the cytoplasm rather than in the nucleus in gastric cancers." (PMID 35747817, 2022). "In the present study, we found that linc01133 was significantly upregulated in gastric cancer tissues compared to non-tumorous gastric tissues." (PMID 35017464, 2022). "It is not clear how linc01133 is regulated in gastric cancer." (PMID 35017464, 2022). "FOS and JUN overexpression increased linc01133 mRNA level in MKN45, SGC7901 and HGC27 gastric cancer cells, but not in AGS cells." (PMID 35017464, 2022). "On the contrary, certain lncRNA showed a downregulation in gastric cancer, for example, in gastric cancer, lncRNA ELF3-AS1 is down-regulated and contributes to cancer inhibition; LINC01133 is downregulated and inhibits tumor development by negatively regulating miR-106a-3p." (PMID 40442738, 2025).
pancreatic cancer (10 papers, 2018 to 2023). "Taken together, LINC01133 contributed to the acquired resistance to ferroptosis in pancreatic cancer cell lines." (PMID 38007473, 2023). "It was reported that linc01133 plays oncogenic roles in pancreatic cancer, hepatocellular carcinoma, renal cell carcinoma, endometrial carcinoma and cervical squamous carcinoma, while in colorectal carcinoma, linc01133 inhibits the malignant progression." (PMID 35017464, 2022). "Moreover, LINC01133 is highly expressed in pancreatic cancer cells as well as in their secreted exosomes." (PMID 35055115, 2022). "Exosomal LINC01133 plays an important role in pancreatic cancer progression." (PMID 34263260, 2021). "Collectively, these data indicate that exosomal LINC01133 plays an important role in pancreatic tumor progression, and targeting LINC01133 may provide a potential treatment strategy for PDAC." (PMID 33824474, 2021). "We have also determined that LINC01133 has significantly higher expression levels in pancreatic cancer tissues compared with the matched adjacent tissues, which suggests that LINC01133 may act as a potential prognostic biomarker and therapeutic target for pancreatic cancer." (PMID 33824474, 2021). "Similarly, LINC01133 could contribute to the tumorigenesis and progression in pancreatic cancer through numerous pathways." (PMID 34854360, 2021). "Besides, considering previous studies in CRC, lung cancer and pancreatic cancer, whether LINC01133 might bind certain proteins or regulate other pathways to exert its inhibitory effect on GC progression remains mysterious." (PMID 30134915, 2018). "It was also identified that LINC01133 is transactivated by CCAAT/enhancer-binding protein β (CEBPB) and positively modulates cell proliferation via activating cyclin G1 expression in pancreatic cancer." (PMID 35055115, 2022). "In pancreatic cancer cells and tissues, qRT-PCR indicated the relative expression of LINC01091, LINC01133, TRPC7-AS1, and LINC00973." (PMID 36371178, 2022). "LINC01133 promotes the proliferation, migration, invasion, and epithelial-to-mesenchymal transition (EMT) of pancreatic cancer cells through Wnt/β-catenin pathway." (PMID 34263260, 2021). "We also observed that LINC01133 promoted the proliferation, migration, invasion, and epithelial–mesenchymal transition (EMT) of pancreatic cancer cells." (PMID 33824474, 2021). "In pancreatic cancer, 11 lncRNAs, A2M-AS1, DLEU2, LINC01133, LINC00675, MIR155HG, SLC25A25-AS1, LINC01857, LOC642852 (LINC00205), ITGB2-AS1, TSPOAP1-AS1 and PSMB8-AS1 were identified and validated on a pancreatic ductal adenocarcinoma expression dataset." (PMID 31164492, 2019). "However, a recent report showed that LINC01133 has low expression in CRC and indicated that LINC01133 acts as a tumor suppressor in this disease, which is in contrast to our findings in pancreatic cancer." (PMID 33824474, 2021).
colorectal cancer (8 papers, 2018 to 2024). A primary or metastatic malignant neoplasm that affects the colon or rectum. "Recent publications have revealed that LINC01133 is significantly reduced in colorectal cancer and is considered as a potential tumor suppressor in cancer progression and metastasis." (PMID 34322151, 2021). "While LINC01133 is well characterized as an important factor in colorectal cancer progression and metastasis, LINC00483 is poorly characterized." (PMID 33375322, 2020). "The long intergenic non-coding RNA 1133 (LINC01133) gene on chromosome 1q23.2 is down-regulated in colorectal cancer, while an up-regulation was reported in different types of lung cancer." (PMID 30518158, 2018). "For example, LINC01133, which is downregulated by TGF-β, inhibits EMT and metastasis in colorectal cancer." (PMID 29416704, 2018). "Nevertheless, some studies have shown low LINC01133 expression in colorectal cancer (CRC), and LINC01133 overexpression was found to inhibit CRC cell metastasis by binding and blocking serine/arginine-rich splicing factor 6 function." (PMID 30134915, 2018). "Mechanistically, LINC01133 acts as key downstream molecule in the TGF-β pathway and inhibits the EMT in colorectal cancer by directly binding to SRSF6 (serine and arginine rich splicing factor 6) as a target mimic." (PMID 29416704, 2018).
lung cancer (6 papers, 2018 to 2023). A malignant neoplasm involving the lung. "LINC01133 exerts oncogenic functions in nasopharyngeal carcinoma and lung cancer by binding to YBX1 and EZH2, respectively." (PMID 34047479, 2021). "A positive correlation was found between high LINC01133 expression in patients and poor prognosis, and LINC01133 knockdown led to inhibition of the proliferation and invasion of lung cancer and osteosarcoma cells." (PMID 30134915, 2018). "Moreover, TCGA database indicated that the expression of LINC01133 was upregulated in several other tumors, and GSEA results indicated that LINC01133 was connected to pathways related to PAAD, lung cancer, bladder cancer, and colon cancer (Online Resource 2)." (PMID 37138146, 2023).
pancreatic ductal adenocarcinoma (5 papers, 2018 to 2024). An infiltrating adenocarcinoma that arises from the epithelial cells of the pancreas. "Studies report that high expression of LINC01133 in pancreatic adenocarcinoma plays a carcinogenic role, and LINC01133 can be transported to the extracellular space by pancreatic adenocarcinoma cells through exosomes to promote epithelial mesenchymal transformation of pancreatic duct adenocarcinoma." (PMID 37173624, 2023). "Interestingly, a recent study demonstrated that the C/EBPβ transcription factor could bind the promoter of LINC01133 and upregulated the expression of LINC01133 in pancreatic ductal adenocarcinoma." (PMID 30134915, 2018). "In addition, tumor-derived exosomal LINC01133 can interact with EZH2 and then promotes H3K27 trimethylation, contributing to pancreatic ductal adenocarcinoma tumor growth and epithelial-mesenchymal transition in vivo." (PMID 34868904, 2021).
breast cancer (4 papers, 2019 to 2025). A primary or metastatic malignant neoplasm involving the breast. "In this study, we found that the LINC01133 expression was significantly down‐regulated in breast cancer samples and was associated with progression and poor prognosis of breast cancer." (PMID 31557401, 2019). "In summary, these findings showed for the first time that LINC01133 was down‐regulated in breast cancer cells and tissues, and the downregulation of LINC01133 is associated with progression and poor prognosis of breast cancer patients." (PMID 31557401, 2019). "Functional experiments of cell proliferation, including CCK8, colony formation, and EdU, demonstrated that inhibition of LINC01133 notably promoted, while overexpression of LINC01133 suppressed, the proliferation of ER+ breast cancer cells." (PMID 40641925, 2025). "Functionally, LINC01133 inhibited migration and invasion in vitro and metastasis in vivo of ER+ breast cancer cells." (PMID 40641925, 2025). "Transwell assay demonstrated that the downregulation of LINC01133 importantly strengthened the migration and invasion capabilities of ER+ breast cancer cells, whereas LINC01133 upregulation substantially reduced these abilities." (PMID 40641925, 2025). "Investigating the distinct expression patterns of LINC01133 across various breast cancer subtypes highlights the importance of elucidating its precise expression profiles and underlying mechanisms in each subtype." (PMID 40641925, 2025). "LINC01133 was dramatically downregulated in ER+ breast cancer, which results in unfavorable prognosis." (PMID 40641925, 2025). "LINC01133 exhibits opposing expressing patterns across different breast cancer subtypes, yet its roles and mechanisms in ER+ breast cancer remain a loaded question." (PMID 40641925, 2025). "In this research, our objective is to elucidate the function and molecule mechanisms of LINC01133 in ER+ breast cancer." (PMID 40641925, 2025). "The overexpression of LINC01133 inhibits the invasion and metastasis of breast cancer cells both in vitro and in vivo via a transcription-mediated regulatory mechanism." (PMID 35747817, 2022). "LINC01133 inhibits breast cancer invasion and metastasis through repressing SOX4 expression by recruiting EZH2 to SOX4 promoter." (PMID 33834618, 2021). "The expression of LINC01133 was examined in 74 human breast cancer tissues and adjacent normal tissues using qRT‐PCR with normalization to GAPDH." (PMID 31557401, 2019). "The results showed that the LINC01133 expression was significantly decreased in breast cancer cell lines compared with that in the normal breast epithelial cell line MCF‐10A." (PMID 31557401, 2019). "The results demonstrated that the downregulation of LINC01133 predicted a poor prognosis in breast cancer patients." (PMID 31557401, 2019). "The results showed that the expression of LINC01133 was significantly down‐regulated in breast cancer tissues than that in the corresponding non‐cancerous tissues." (PMID 31557401, 2019). "Here, for the first time, we showed that LINC01133 exerted anti‐oncogenic functions in breast cancer cells by inhibition of SOX4." (PMID 31557401, 2019). "Collectively, these findings demonstrated that a notable reduction in LINC01133 might play an indispensable function in the breast cancer progression, especially in ER+ breast cancer." (PMID 40641925, 2025). "Additionally, low LINC01133 predicted shorter overall survival and metastasis-free survival compared to those with high LINC01133 in ER+ breast cancer patients." (PMID 40641925, 2025). "Likewise, real-time PCR assay uncovered that LINC01133 was robustly decreased in ER+ breast cancer (BCa, n = 12) relative to corresponding adjacent normal breast tissues (ANT, n = 12)." (PMID 40641925, 2025). "In addition, LINC01133 levels in breast cancer tissues are much lower than those in normal breast tissues." (PMID 40641925, 2025).
breast cancer (continued). "GSEA analysis revealed a notable trend of proliferation traits focused on the subset of ER+ breast cancer exhibiting low levels of LINC01133 suggesting that LINC01133 might mediate the proliferation of ER+ breast cancer." (PMID 40641925, 2025). "We further explore the functional role of LINC01133 in breast cancer cells." (PMID 31557401, 2019). "However, further studies are still needed to clarify other potential target of LINC01133 and molecular regulation mechanism in breast cancer." (PMID 31557401, 2019). "Moreover, we revealed that LINC01133 inhibited invasion and metastasis in breast cancer, partly through binding with EZH2 to mediate SOX4 transcriptional inhibition." (PMID 31557401, 2019). "Moreover, rescue experiments further confirmed that LINC01133 functional acted as an anti‐oncogene, at least partly, via repressing SOX4 in breast cancer." (PMID 31557401, 2019). "Our findings revealed the downregulation of LINC01133 in ER+ breast cancer and provided novel insight to the role of METTL3/YTHDF2/LINC01133/IGF2BP2 axis in ER+ breast cancer, which might offer a novel perspective in the design and development of novel anticancer drugs." (PMID 40641925, 2025). "To further determine potential targets of LINC01133 involved in breast cancer invasion and metastasis, we investigate the expression of metastatic regulators and found that both mRNA level and protein level of SOX4 was significantly increased in response to LINC01133 knockdown." (PMID 31557401, 2019).
lung squamous cell cancer (4 papers, 2016 to 2023). "LINC01133 was first reported in 2015 to be highly expressed in lung squamous cell carcinoma and then its role in tumors has been fully explored." (PMID 34854360, 2021). "LINC01133 is previously found to be over-expressed in lung squamous cell cancer (LSCC) and knockdown its expression inhibits LSCC cells invasion." (PMID 26840083, 2016). "Notably, recently studies have shown linc01133 to be upregulated in lung squamous cell cancer, and also that the expression level of lin01133 is indicative of patient survival." (PMID 27027352, 2016).
osteosarcoma (4 papers, 2018 to 2021). A usually aggressive malignant bone-forming mesenchymal neoplasm, predominantly affecting adolescents and young adults. "In osteosarcoma, LINC01133 promotes tumor growth as a miR‐422a sponge." (PMID 34047479, 2021). "Furthermore, LINC01133 was shown to sponge the miR-422a to aggravate the tumorigenesis of human osteosarcoma." (PMID 30518158, 2018). "Recently, it has been verified that LINC01133 is involved in multiple types of malignant tumors, such as LSCC, osteosarcoma, cervical cancer, hepatocellular carcinoma, colorectal cancer (CRC), and gastric carcinoma." (PMID 33824474, 2021).
ovarian carcinoma (4 papers, 2021 to 2022). A malignant neoplasm originating from the surface ovarian epithelium. "LINC01133 was reported to repress ovarian cancer cell proliferation, invasion, migration, and tumorigenic ability." (PMID 34461858, 2021). "Expression of LINC01133 has been found to be enhanced in epithelial ovarian cancer cell lines." (PMID 36042493, 2022). "Functionally, LINC01133 enhances migration and invasiveness of ovarian cancer cells." (PMID 36042493, 2022). "A similar contradiction regarding LINC01133 function also exists in ovarian cancer." (PMID 35747817, 2022).
hepatocellular carcinoma (3 papers, 2021 to 2022). A malignant tumor that arises from hepatocytes. "LINC01133 could promote the malignant behaviors in several tumor, such as lung adenocarcinoma, hepatocellular carcinoma, triple-negative breast cancer and nasopharyngeal carcinoma." (PMID 34854360, 2021).